CRH (corticotropin releasing hormone)
Diseases named in the same sentence as CRH in open-access papers (continued):
Sharing a sentence is not in itself a finding about the gene and the disease.
depression (continued). "A combined DEX/corticotropin-releasing hormone (CRT) test, the cortisol-awakening response (CAR), and individual cortisol levels or profiles were also proposed for diagnosing depression in addition to Carroll’s DST but are not discussed in this review." (PMID 37241007, 2023). "Typical depression exhibited increased levels of adrenocorticotropic hormone (ACTH) and/or corticotropin-releasing hormone (CRH) without proper regulation by the hippocampus." (PMID 32153449, 2020). "Elevated levels of ACTH and CORT in serum and negative feedback of CRH level confirmed that ACTH injection induced hyperactivity of HPA axis, which was reported to be closely related to depression." (PMID 31307473, 2019). "In a large depression sample, recent suicide attempters showed a reduced HPA response in the dex/CRH test, and previous suicide attempts were negatively correlated with CRH-induced ACTH and cortisol levels independent of depression severity." (PMID 36032226, 2022). "The significant higher concentration of CRH and ACTH, induced by the initial injection of interferon (IFN)-α, has been found in patients with the subsequent development of depression during IFN-α treatment than in those without depression." (PMID 23874274, 2013). "The hypercortisolic state tends to be mild in patients with depression and a positive cortisol response to insulin-induced hypoglycemia, an attenuated ACTH response to the CRH test, and a negative ACTH response to the desmopressin test can be observed, although a wide overlap may exist." (PMID 31726770, 2019).
hypercortisolism (51 papers, 2009 to 2026). "During pregnancy, the activity of the maternal HPA-axis gradually increases over time toward a state of hypercortisolism that is caused by the steadily increasing production of corticotropin-releasing hormone (CRH) in the placenta and fetal membranes)." (PMID 25071717, 2014). "To date, the literature on PPGLs (both pheochromocytomas and paragangliomas have been described) associated with hypercortisolemia has primarily focused on tumors secreting ectopic ACTH and/or CRH, which predominantly present as overt Cushing syndrome." (PMID 40578302, 2026). "Midnight salivary and 24-hour urinary free cortisol tests confirmed hypercortisolism, consistent with a pituitary source which was confirmed with a peripheral corticotropin-releasing hormone (CRH) stimulation test." (PMID 40642336, 2025). "Once hypercortisolism was demonstrated, a peripheral corticotropin-releasing hormone (CRH) stimulation test was performed to localize the source of ACTH excess." (PMID 40642336, 2025). "For both CRH interventions, stopping treatment led to a rapid return to hypercortisolemia (F and EV4)." (PMID 39849227, 2025). "Excessive functionality of the hypothalamic-pituitary-adrenal axis (HPAa) and corticotropin-releasing hormone (CRH) and/or arginine vasopressin (AVP) pathways causes secondary hypercortisolism causes pseudo-Cushing's symptoms." (PMID 41024930, 2025). "In this regard, more than 40% of depressed patients exhibited hypercortisolemia, increased CRH production or reduced ACTH release, with hypercortisolemia being associated with MDD severity and MDD-associated psychosis." (PMID 39763658, 2024). "This dysregulation has been characterized in FM by mild hypocortisolemia, hyperactivity of pituitary ACTH release to CRH, and glucocorticoid feedback resistance, while only mild dysregulation signs, as hypercortisolemia, have been found in CLBP." (PMID 34828579, 2021). "CD is confirmed by an IPS/P ratio of ≥2:1 at baseline, and/or a CRH-stimulated IPS/P ratio of ≥3:1 in the setting of hypercortisolemia, usually defined by an elevated 24-h urinary free cortisol collected on the day prior to testing." (PMID 29757946, 2018). "Long-lasting stress, in specific, is believed being maintained by enduring imbalance of the HPA, through secretion of the corticotropin-releasing hormone (CRH) resulting in hypercortisolism." (PMID 27147943, 2016). "EAS tumours (33.3%) were shown to synthesize either ACTH or CRH responsible for the development of hypercorticism or coexpress ACTH and CRH (n = 5; 27.8%)." (PMID 23509456, 2013). "Subsequently, a laboratory test for plasma CRH revealed that it was 10 pg/ml, at the upper limit of normal (0-10 pg/ml), in spite of concurrent hypercortisolism." (PMID 20807418, 2010). "Patients with MDD, despite hypercortisolism, show inappropriately normal levels of corticotropin-releasing hormone (CRH) and plasma adrenocorticotropin (ACTH) in the cerebrospinal fluid, which might implicate impaired negative feedback." (PMID 38927393, 2024). "Pathophysiology of cyclic hypercortisolemia may involve hypothalamic dysfunction with different degree of corticotroph cell response to neurotransmitters such as corticoliberin (CRH), dopamine, neuroepinephrine, serotonine and/or γ-aminobutyric acid (GABA)." (PMID 33967962, 2021). "Management: CS treatment in pregnancy should be individualized because improvements or exacerbations of CS may occur; irregular production of placental corticotropin-releasing hormone (CRH) exacerbates hypercortisolemia during pregnancy." (PMID 30836653, 2019). "Cushing’s syndrome (CS) due to chronic exposure to endogenous hypercortisolism may be caused by a pituitary adenoma, an adrenocortical tumor or ectopic adrenocorticotropic hormone (ACTH) or corticotropin-releasing hormone (CRH) production." (PMID 25799396, 2015).
hypercortisolism (continued). "Although apparently contradictory, normal CSF CRH levels taken hourly for twenty-four hours in melancholic depressed patients were inappropriately in the normal range in the context of pronounced hypercortisolism, which should have suppressed hypothalamic CRH neurons that release CRH into the CSF." (PMID 25878903, 2015). "Interestingly, increased methylation of SNPs in the FKBP5 gene (e.g., rs9296158) and some CRHR1 gene polymorphisms that produce high levels of CRH are associated with cortisol hypersensitivity and hypercortisolism and represent a distinct PTSD phenotype from that characterized by hypercortisolism." (PMID 37374323, 2023). "It is well known that pregnancy could be considered a “physiological” state of hypercortisolism, based on the higher levels of cortisol binding globulin enhanced by placental estrogen and placental corticotropin-releasing hormone that lead to an increase of free and total plasma cortisol levels." (PMID 34846622, 2022). "Management of GRS is aimed at suppression of the HPA axis to reduce CRH and ACTH-mediated hypercortisolism, mineralocorticoid, and/or androgen excess." (PMID 39850725, 2025). "CRH secretion from ectopic sources can stimulate ACTH secretion via both local autocrine and systemic endocrine mechanisms, exacerbating hypercortisolemia." (PMID 40927294, 2025). "CRH test alone is widely used to diagnose hormone excess source in ACTH-dependent CS, but it was also studied to discern functional and neoplastic hypercortisolism." (PMID 37079177, 2023). "Differentiation of the origin of hypercortisolemia can be based on morning plasma ACTH, and CRH stimulation test." (PMID 33967962, 2021). "Identification of the origin of hypercortisolemia in cyclic Cushing’s syndrome is based on the same tests as in the classic form of the disease: morning plasma ACTH, CRH stimulation test, rarely HDDST." (PMID 33967962, 2021). "The diagnosis of EAS was based on the clinical presentation, hypercortisolemia with high ACTH levels, high dose dexamethasone suppression test and/or corticotropin-releasing hormone tests." (PMID 33237923, 2020). "In obesity, persistent CRH- and vasopressin-mediated ACTH secretion may lead to chronic mild hypercortisolism and a state of allostatic overload in some individuals." (PMID 41515266, 2026). "Additionally, placental CRH stimulates maternal ACTH and cortisol secretion, mimicking the hypercortisolism seen in CS and complicating the diagnosis." (PMID 40226089, 2025). "Endogenous neoplastic hypercortisolism or Cushing syndrome (CS) may be due to a corticotropin (ACTH)-secreting pituitary adenoma, an ACTH- (and rarely CRH) producing ectopic tumor, or ACTH-independent adrenal nodular disease." (PMID 38681763, 2024). "Another theory, depending on the depressed patient subgroups, is that long-lasting chronic stress may be maintained by an enduring imbalance of the HPA axis via CRH and ACTH secretion and hypercortisolism." (PMID 38927393, 2024). "Moreover, PVN CRH activity is also a driver of increased SNS tone (adding to the insulin resistance potentiation of hypercortisolemia) that, in turn, can potentiate increases in plasma corticosteroid levels." (PMID 37686060, 2023). "The biological explanation for the heterogeneity in the ACTH response to dexamethasone-CRH in the different forms of non-neoplastic hypercortisolism is not known." (PMID 37409223, 2023). "LNSC, midnight plasma cortisol levels, and the dexamethasone-CRH test have a good performance to differentiate CS from nonneoplastic hypercortisolism." (PMID 37560300, 2023). "The DDAVP and/or combined DST/CRH tests have been used to distinguish patients with Cushing’s disease from those with non-tumoral hypercortisolism." (PMID 33266265, 2020). "There is limited data of dexamethasone-CRH use in diagnosis of recurrence and optimal cutoff levels to rule out non-neoplastic hypercortisolism during recurrence are yet to be established." (PMID 31787930, 2019).
hypercortisolism (continued). "CRH and ACTH-secreting tumours produce the clinical picture of hypercorticism." (PMID 23509456, 2013). "Patients with EAS will have a ratio less than 2 before and after CRH administration because the endogenous hypercortisolism suppresses pituitary ACTH release through negative feedback mechanisms (sensitivity 97%, specificity 100%)." (PMID 19829770, 2009). "In addition, hypercortisolemia without Cushingoid features and unsuppressed serum cortisol levels in both the Dex suppression and Dex-CRH tests indicated resistance to glucocorticoid effects." (PMID 40452801, 2025). "Laboratory tests in an external hospital had revealed adrenocorticotrophic (ACTH) hormone independent hypercortisolemia with lack of cortisol suppression in the 8 mg dexamethasone suppression test and missing stimulation of cortisol in the corticotropin releasing hormone (CRH) test." (PMID 36255590, 2023). "Indeed, previous dexamethasone suppression (i.e., Dex-CRH test) may prevent effective corticotroph response in NNH/pCS patients, enhancing their discrimination from neoplastic hypercortisolism." (PMID 37079177, 2023). "Hypercortisolemia is related to overstimulation of the hypothalamic–pituitary–adrenal (HPA) axis, with increased secretion of hypothalamic corticotropin-releasing hormone (CRH) and/or pituitary adrenocorticotropic hormone (ACTH) resulting in elevated glucocorticoid secretions such as cortisol." (PMID 35622772, 2022). "Currently it has been proposed for ruling out non-neoplastic hypercortisolism, but may have lower sensitivity (75–90%) and specificity (90–92%) than CRH stimulation test after dexamethasone suppression." (PMID 31787930, 2019). "Even considering the wide variability in ACTH, hypercortisolemia without a significant increase in ACTH suggests a peripheral rather than central alteration, such as hyperactivity of the CRH–NE system." (PMID 38927393, 2024).
Cushing syndrome (41 papers, 2006 to 2026). Cushing's syndrome (CS) encompasses a group of hormonal disorders caused by prolonged and high exposure levels to glucocorticoids that can be of either endogenous (adrenal cortex production) or exogenous (iatrogenic) origin. "Isolated ectopic secretion of CRH is an extremely rare cause of Cushing’s syndrome, but its potentially life-threatening course necessitates urgent diagnostic evaluation and treatment." (PMID 40927294, 2025). "Isolated ectopic secretion of corticotropin-releasing hormone (CRH) is an exceedingly rare cause of Cushing’s syndrome (CS), accounting for fewer than 1% of cases." (PMID 40927294, 2025). "Cushing’s disease is most often caused by a pituitary adenoma (specifically pituitary basophilism) or excess production of the corticotropin-releasing hormone that stimulates the synthesis of cortisol by the adrenal glands." (PMID 36742456, 2023). "In some cases of pheochromocytoma-associated ACTH-dependent Cushing’s syndrome, the ectopically secreted hormone is CRH, with ACTH being secreted by pituitary hyperplasia." (PMID 27699708, 2017). "Commonly occurring PES are ACTH or CRH production leading to cushing syndrome, hypercalcemia caused by parathyroid hormone-related protein or syndrome of inappropriate secretion of antidiuretic hormone (SIADH)." (PMID 27349224, 2016). "In our cohort of all PPGLs only 0.8% produced enough ectopic ACTH and/or CRH to present as overt Cushing syndrome." (PMID 40578302, 2026). "Pathological conditions have also been reported as a cause of pituitary hyperplasia, such as ectopic acromegaly and Cushing’s syndrome due to CRH." (PMID 40718387, 2025). "The aim of this study was to evaluate the diagnostic performance of the CRH stimulation test and the overnight 8 mg DST (either alone or in combination) in a large series of patients with confirmed ACTH-dependent Cushing’s syndrome." (PMID 36277711, 2022). "Ectopic secretion of corticotropin-releasing hormone (CRH) can also lead to ACTH-dependent Cushing’s syndrome, which is very rare." (PMID 36213295, 2022). "Very rarely, patients can present with symptoms and signs of Cushing’s syndrome due to ACTH/CRH secretion from the PPGL." (PMID 35205664, 2022). "Ectopic Cushing’s syndrome due to ectopic ACTH&CRH-secreting by pheochromocytoma is extremely rare and can be fatal if not properly diagnosed." (PMID 34905486, 2021). "To date, only two cases with meningioma-induced Cushing’s syndrome have been reported (in 2003 and 2014) and, in contrast to our case, they both were with parietal meningiomas secreting CRH." (PMID 32423480, 2020). "Overall, the CRH‐Tg mouse model aged to 14 weeks recapitulated many features of osteoporosis in Cushing's syndrome and thus, represents a useful model to study GC‐induced osteoporosis and interventions that target the effects of GCs on the skeleton." (PMID 30283880, 2017). "Fortunately, false positives are rare and can occur in cases of EAS during periods of normocortisolism (cyclical Cushing’s syndrome or use of medical therapy for Cushing’s) or in the rare case of ectopic CRH secretion." (PMID 27355856, 2016). "Traditionally used for the differential diagnosis of ACTH-dependent Cushing’s syndrome, the human CRH (hCRH) test was studied in 2009 to differentiate Cushing’s syndrome from states of pseudo-Cushing’s." (PMID 27355856, 2016). "Occasional reports of ACTH/CRH-producing ganglioneuromas presenting clinically as Cushing's syndrome were reported." (PMID 27413558, 2016). "CRH injection coupled with dexamethasone suppression test, is in favor of Cushing’s syndrome with 90% sensitivity and 84% specificity in the presence of peak cortisol > 580 nmol/l and ACTH > 50 pg/ml." (PMID 22710101, 2012). "This case illustrates the importance of considering the ectopic production of CRH in the differential diagnosis for presentations of ACTH-dependent Cushing's Syndrome." (PMID 20807418, 2010).
Cushing syndrome (continued). "The gold standard for the differential diagnosis of pituitary and ectopic ACTH-dependent Cushing’s syndrome is the bilateral inferior petrosal sinus sampling after administration of CRH (1 μg/kg)." (PMID 19829770, 2009). "We describe a hypophosphatemia-related ARDS case report of a 50-year-old woman with ACTH dependent Cushing's syndrome secondary to ectopic CRH production." (PMID 18264630, 2008). "Some authors have speculated that Cushing syndrome may worsen or be revealed during pregnancy because of the placental CRH and ACTH production, but also because of the estrogen-induced increase in CBG, which reduces the negative feedback on ACTH secretion." (PMID 41201503, 2025). "The etiology of the increased ACTH secretion may be due to ectopic Corticotropin-Releasing Hormone (CRH) production as expression of CRH has been reported in advanced melanoma cells and Cushing’s syndrome due to ectopic CRH secretion has been reported." (PMID 30693099, 2019). "Thus, a rat model for Cushing's syndrome was generated by implanting a medullary thyroid carcinoma cell line, which stably over-expressed CRH, into WAG/Rij rats." (PMID 26320859, 2016). "Cushing's Syndrome (CS) which is caused by isolated Corticotropin-releasing hormone (CRH) production, rather than adrenocorticotropin (ACTH) production, is extremely rare." (PMID 20807418, 2010). "As with ACTH-independent Cushing's syndrome due to other causes, patients with PPNAD have low plasma levels of ACTH and show no stimulation of cortisol or ACTH secretion after corticotropin-releasing hormone (CRH) injection." (PMID 16756677, 2006). "Moreover, we know that PPGLs may produce ACTH and/or CRH in ectopic Cushing syndrome resulting from PPGLs." (PMID 40578302, 2026). "Out of the entire retrospective cohort of 616 patients with ACTH-dependent Cushing’s syndrome (Tübingen, n=167 (27%); Munich, n=149 (24%); Vienna, n=118 (19%); Würzburg, n=108 (18%); Milan, n=47 (8%); Berlin, n=27 (4%)), 556 (90%) underwent a CRH stimulation test and/or an overnight 8 mg DST." (PMID 36277711, 2022). "Besides the local effects caused by metastases in the liver, bone, lung, and mediastinal region, patients with advanced MTC may suffer from diarrhea (due to hypercalcitoninemia) or from Cushing’s syndrome due to ectopic ACTH or CRH secretion." (PMID 29774010, 2018). "To date, there have been reports of PPGLs that synthesize either ACTH or corticotropin-releasing hormone (CRH), leading to the manifestation of ectopic Cushing syndrome in affected individuals." (PMID 40578302, 2026). "We retrospectively analyzed data from patients with ACTH‐dependent Cushing syndrome and inconclusive pituitary‐MRI who underwent IPSS with corticotropin‐releasing hormone (CRH) stimulation between 2015 and 2025." (PMID 40765079, 2025). "We presented a rare case of ectopic Cushing syndrome due to ACTH- and CRH-secreting pheochromocytoma." (PMID 41334448, 2025). "Prior to this case, there is only one previously reported case of HB presenting with endocrine manifestations, occurring in a 6-year-old female who had Cushing syndrome and whose liver tumor was found to be secreting ACTH, CRH, and PTHrP." (PMID 36551621, 2022). "In the present study, we performed phenotypic characterization of the bones of CRH‐Tg mice and determined that they exhibit several properties consistent with GIO in humans with Cushing's syndrome." (PMID 30283880, 2017). "Magnetic resonance imaging (MRI) of the pituitary, the corticotropin-releasing hormone (CRH) test and the high-dose dexamethasone suppression test are the main tests for the differential diagnosis of ACTH-dependent Cushing’s syndrome." (PMID 27355856, 2016). "68Ga CRH PET-CT targets CRH receptors, identifying corticotropinoma and providing surgeons with valuable information for intraoperative tumor navigation and distinguishing pituitary and extrapituitary sources of ACTH-dependent Cushing's syndrome." (PMID 39677352, 2024).